SLC19A1 (solute carrier family 19 member 1)
Diseases named in the same sentence as SLC19A1 in open-access papers (continued):
Sharing a sentence is not in itself a finding about the gene and the disease.
juvenile idiopathic arthritis (3 papers, 2015 to 2023). Juvenile idiopathic arthritis (JIA) is the term used to describe a group of inflammatory articular disorders of unknown cause that begin before the age of 16 and last over 6 weeks. "In our analysis, the most common functional variants of ATIC, ITPA, and SLC19A1 were associated with clinical response to methotrexate evaluated as remission stable for a 6-months period, as ACRPed score and as change in Juvenile Arthritis Disease Score (JADAS) in 69 patients with JIA." (PMID 25852556, 2015).
neutropenia (3 papers, 2022 to 2025). A decrease in the number of neutrophils found in the blood. "Patients with SLC19A1 rs4149056 TC or CC genotype had a higher risk for neutropenia (OR: 3.172, 95% CI: 1.310–7.681, P = 0.011)." (PMID 36742186, 2022). "Neutropenia was related to SLC19A1 rs4149056 (odds ratio [OR]: 3.172, 95% confidence interval [CI]: 1.310–7.681, P = 0.011)." (PMID 36742186, 2022).
cervical cancer (2 papers, 2018 to 2021). A primary or metastatic malignant neoplasm involving the cervix. "Moreover, a high level of SLC19A1 correlated with a poor prognosis for all patients with cervical cancer (p = 0.031)." (PMID 33997099, 2021). "In addition, the genomic deletion of SLC19A1 increases the IC50 of PEM in human cervical cancer HeLa cells." (PMID 29682186, 2018). "In this study, the authors discovered the multiple genes in HPV-negative cervical cancer, including PRAME, HMGA2, ETV4, MEX3A, TM7SF2, SLC19A1, and TTYH3, which could contribute to HPV-negative cervical cancer development." (PMID 33997099, 2021). "In this study, we first identified that SLC19A1 might play an important role, especially in HPV-negative cervical carcinoma." (PMID 33997099, 2021). "Overexpression of SLC19A1 was detected in C33A cell line, whereas low expression was observed in HPV-positive cell lines, consistent with the results obtained from human tissues, implying SLC19A1 has potential relevance in the carcinogenesis of HPV-negative cervical cancer." (PMID 33997099, 2021).
congenital heart disease (2 papers, 2023 to 2024). A heart disease that is present at birth. "The most frequently studied variant in the SLC19A1 gene associated with congenital heart disease in humans is the missense mutation in the exon 2 of the gene, which results in an amino acid change on position 27 in the SLC19A1 protein; namely, histidine is replaced by proline." (PMID 39062651, 2024). "A variant in the SLC19A1 gene that is associated with congenital heart disease in humans." (PMID 39062651, 2024).
glioma (2 papers, 2021 to 2025). A benign or malignant brain and spinal cord tumor that arises from glial cells (astrocytes, oligodendrocytes, ependymal cells). "Further prognostic analysis revealed that patients with high SLC19A1 expression had significantly poorer outcomes among all glioma samples." (PMID 40149548, 2025). "Kalan–Meier curves suggest that higher SLC19A1 promoter methylation level predicts a better prognosis in BLAD, BRCA, basal-like BRCA, glioma, SKCM, and SKCM metastasis." (PMID 40149548, 2025). "We found that compared to grade I–II gliomas, grade III–IV gliomas exhibited relatively higher SLC19A1 expression, suggesting a potential role of SLC19A1 in promoting the malignant progression of gliomas." (PMID 40149548, 2025).
liver disease (2 papers, 2023 to 2025). "Also, the analysis of the reactome of SLC19A1 revealed its direct relation to the core transcription factor CREB1, which has been proposed as a potential therapeutic target for liver disease." (PMID 36830876, 2023).
lung carcinoma (2 papers, 2019 to 2020). "We found that females who in the reduced folate carrier gene, SLC19A1, had A allele variant at the nucleotide position c.80 showed increased lung cancer risk." (PMID 30939165, 2019). "In women, the SLC19A1 c.80AA genotype was associated with a higher risk of lung cancer as compared to the GG genotype (OR = 3.14, 95% CI: 1.32–7.46, P = 0.01)." (PMID 30939165, 2019). "Additionally, in a subset of women, an increased risk of lung cancer development was associated with the SLC19A1 c.80AA genotype (c.80AA versus GG OR, 3.14; 95% CI, 1.32–7.46; P = P = 0.010)." (PMID 30939165, 2019). "In men, inversely, the SLC19A1 c.80AA genotype was associated with a protection against lung cancer as compared to the GG genotype (OR = 0.39, 95% CI: 0.17–0.91, P = 0.03), but this association was no longer significant after correction for multiple comparisons." (PMID 30939165, 2019). "Further, the female carriers of the SLC19A1 c.80A allele belong to the group exhibiting increased lung cancer incidence pointing that certain associations between the folate/homocysteine pathway and the development of smoking-related lung cancer are sex-specific." (PMID 30939165, 2019).
Multiple Myeloma (2 papers, 2022 to 2025). "SLC19A1 has also been recognized as a biomarker associated with poor prognosis in multiple myeloma." (PMID 41376620, 2025).
neural tube defect (2 papers, 2016 to 2023). A congenital defect characterized by failure of the neural tube to close completely; this results in the presence of openings in the brain or spinal cord. "DeMarco and colleagues reported that, while the SLC19A1-A80G variant is common in the Italian population (0.47), the allelic frequency was higher among neural tube defects (NTDs) cases and their parents than in unaffected controls." (PMID 36830876, 2023). "Recent genetic studies recognized the contribution of the SLC19A1 gene to neural tube defects (NTD)." (PMID 27213354, 2016).
non-small cell lung carcinoma (2 papers, 2013 to 2021). A group of at least three distinct histological types of lung cancer, including non-small cell squamous cell carcinoma, adenocarcinoma, and large cell carcinoma. "An analysis of the Han patients with non-small cell lung cancer who were only received pemetrexed treatment showed that the SLC19A1 rs1051298 (c.*746 C > T) increases the risk of all adverse drug reactions of pemetrexed treatment in different cycles." (PMID 34798807, 2021).
renal carcinoma (2 papers, 2011 to 2013). A carcinoma arising from the epithelium of the renal parenchyma or the renal pelvis. "We utilized data from a recent genome-wide association study (GWAS) of renal cancer with over 3700 Caucasian cases and 8400 controls to look specifically at the association between the two significant SLC19A1 SNPs identified in our study and RCC risk in the GWAS population." (PMID 22039442, 2011). "Supporting our findings, the two significant SLC19A1 SNPs in our study were also associated with RCC in a recent GWAS study of renal cancer, though not at a level of genome-wide significance." (PMID 22039442, 2011). "Variation in SLC19A1 has not been studied in relation to renal cancer, but epidemiologic studies have examined the association of this gene with other cancers." (PMID 22039442, 2011).
abdominal aortic aneurysm (1 paper, 2011). Enlargement and ballooning of the vessel that supplies arterial blood to the abdomen, pelvis and legs. "The nonsynonymous SLC19A1 rs1051266 SNP was previously associated with blood folate levels, and risk of intracranial aneurysm, but not with homocysteine or abdominal aortic aneurysm." (PMID 22103680, 2011).
and renal pelvis cancers (1 paper, 2025). "Specifically, in ESCA, ureter and renal pelvis cancers, and urothelial carcinoma, higher SLC19A1 expression was associated with poorer response." (PMID 40149548, 2025). "Regarding ICI therapy, patients with low SLC19A1 expression in ESCA, ureter and renal pelvis cancers, and urothelial cancers are more likely to achieve survival benefits, whereas those with high SLC19A1 expression in GBM and STAD are more likely to benefit from the treatment." (PMID 40149548, 2025).
B-cell acute lymphoblastic leukemia (1 paper, 2023). A neoplasm of lymphoblasts committed to the B-cell lineage, typically composed of small to medium-sized blast cells. "In addition, miR-5189, miR-595, and miR-6083 that might affect SLC46A1, SLC19A1, and SLCO1A2 MTX transport gene regulation and could affect MTX levels in patients with B-cell acute lymphoblastic leukemia." (PMID 37971595, 2023).
bladder tumor (1 paper, 2022). "Recent studies showed that the mRNA expression levels of SLC19A1 were markedly increased in bladder tumor specimens." (PMID 35958555, 2022).
colorectal adenoma (1 paper, 2011). An adenoma that arises from the colon or rectum. "A recent study examined tag SNPs of one-carbon genes and found five SNPs in SLC19A1 that were significantly associated with risk of colorectal adenomas, including rs1051266." (PMID 22039442, 2011).
coronary artery disease (1 paper, 2011). "The 5' region SLC19A1 rs1131596 SNP was associated with reduced RBC folate levels in coronary artery disease patients and decreased SLC19A1 protein expression." (PMID 22103680, 2011).
folate (1 paper, 2020). "As an adaptation to folate deficiency, the methyl donor-deficient group showed activated transcription of folate receptor and Slc19a1 (reduced folate carrier protein) in the fetal liver." (PMID 32384688, 2020).
Nausea (1 paper, 2021). A sensation of unease in the stomach together with an urge to vomit. "The objective for this study was to investigate whether MTX-induced nausea was associated with selected SNPs in candidate genes encoding MTX transporter proteins (SLCO1B1, SLCO1B3, SLC19A1, ABCB1, ABCC2), the MTHFR enzyme (MTHFR) and the 5-HT3-receptor (HTR3A, HTR3B), in children with JIA." (PMID 33794950, 2021).
oligodendroglioma (1 paper, 2025). A well-differentiated (WHO grade II), diffusely infiltrating neuroglial tumor, typically located in the cerebral hemispheres. "Four of these were similarly associated with longer survival within individual diffuse glioma subtypes: lnc-GBMT-7, lnc-GBMT-10, and lnc-PNMA8C-5 within GBM and lnc-SLC19A1-12 within GBM and oligodendroglioma." (PMID 40346283, 2025).
osteoporosis (1 paper, 2020). A condition of reduced bone mass, with decreased cortical thickness and a decrease in the number and size of the trabeculae of cancellous bone (but normal chemical composition), resulting in increased fracture incidence. "Furthermore, specific allele combinations of CD320, TCN2, SLC19A1, and SLC19A2 may contribute to increased susceptibility to osteoporosis and OVCF." (PMID 32498429, 2020). "In the present study, we explored possible associations between SNPs located in the 3 ́–UTR of the CD320, TCN2, SLC19A1, and SLC19A2 genes and osteoporosis and OVCFs in 301 postmenopausal women." (PMID 32498429, 2020). "Our analyses therefore suggest that the allelic combinations of CD320, TCN2, SLC19A1, and SLC19A2 genes could play a role in the pathogenesis of osteoporosis and OVCF." (PMID 32498429, 2020). "The genotype and allele frequencies of the CD320 rs9426C>T, TCN2 rs10418 C>T, SLC19A1 rs1051296 G>T, and SLC19A2 rs16862199 C>T SNPs were compared between control subjects and osteoporosis patients with or without OVCF." (PMID 32498429, 2020).
psoriasis (1 paper, 2025). An autoimmune condition characterized by red, well-delineated plaques with silvery scales that are usually on the extensor surfaces and scalp. "Thus, this study demonstrated an association between polymorphisms in the SLC19A1 rs1051266 and COL18A1 rs9977268 genes and the need to switch from methotrexate to biologic therapy in patients with moderate-to-severe psoriasis." (PMID 41590498, 2025).
renal cell carcinoma (1 paper, 2011). "In conclusion, we comprehensively examined genetic variation in 13 genes associated with one-carbon metabolism using a tag SNP approach and identified a novel association between SLC19A1 and renal cell cancer." (PMID 22039442, 2011).
cancer (23 papers, 2010 to 2025). A tumor composed of atypical neoplastic, often pleomorphic cells that invade other tissues. "Previous pan-cancer profiling and multi-omics analyses have identified SLC19A1 as a novel unfavorable prognostic marker, closely associated with immune suppression and genomic instability." (PMID 41376620, 2025). "Although no specific patterns of T-reg cells and cancer associated fibroblasts were identified, myeloid-derived suppressor cells (MDSCs) were found to be positively associated with SLC19A1 in majority of the cancer analyzed." (PMID 40149548, 2025). "For the rest of cancers analyzed, SLC19A1 was associated with at least one type of regulators of these three RNA modifications." (PMID 40149548, 2025). "These encouraging findings have inspired us to consider the value of SLC19A1 in risk stratification and bedside decision making for cancer patients." (PMID 40149548, 2025). "Briefly, SLC19A1 was widely dysregulated at the transcriptomic level in different cancers and commonly associated with poor prognosis on a pan-cancer scale." (PMID 40149548, 2025). "Considering distinct tumor microenvironment pattern and neoplastic behavior across different cancers, novel parameters are required to facilitate the risk stratification by SLC19A1." (PMID 40149548, 2025). "Specifically, SLC19A1 expression correlated positively with T-regs, cancer-associated fibroblasts, and MDSCs in KIRC and SKCM-primary." (PMID 40149548, 2025). "Univariate Cox analysis of OS, DSS, and PFI indicated that SLC19A1 is more frequently associated with an increased risk across different cancers." (PMID 40149548, 2025). "At the protein level, the expression of SLC19A1 in cancers and normal tissue was compared, showing that the protein encoded by SLC19A1 is expressed differentially between six types of cancers, including BRCA, GBM, LUSC, LIHC, UCEC, and LUAD." (PMID 40149548, 2025). "In summary, these findings suggest that SLC19A1 is associated with cancer immunity and immune checkpoint defects in various cancers." (PMID 40149548, 2025). "SLC19A1 dysfunction has been associated with fetal abnormalities, megaloblastic anemia, neurologic disorders, cardiovascular disease, and cancer." (PMID 37438132, 2023). "SLC19A1’s genetic variants affect antifolate response, showing a crucial role in the treatment of cancers and inflammatory diseases such as rheumatoid arthritis, psoriasis, and inflammatory bowel disease." (PMID 37438132, 2023). "The variants in the SLC19A1 gene have been identified to be associated with many cancers, and it has been found to be related to the variable response to methotrexate (MTX) and cancer-related compounds." (PMID 36005189, 2022). "Although a heterogeneous response profile to ICI was identified in some cancers, for classical chemotherapies and PD-1 treatment, SLC19A1 could be employed for risk stratification in specific cancers." (PMID 40149548, 2025). "Our findings suggest that SLC19A1 is linked to genomic instability and may contribute to the maintenance of cancer stemness and chemoresistance in neoplastic cells." (PMID 40149548, 2025). "Therefore, the expression of SLC19A1 is associated with the epigenetic modification status, and the methylation of its promoter predicts a better prognosis in several types of cancers." (PMID 40149548, 2025). "In order to further study SLC19A1’s association with cancer immunity, a deconvolution algorism was applied to determine the immune infiltration based on the transcriptomic data of the TCGA pan-cancer cohorts." (PMID 40149548, 2025). "Indeed, decreased expression or loss-of-function mutations of SLC19A1 in cancers would result in resistance to antifolate treatments." (PMID 36575193, 2022). "Existing evidence for an association between SLC19A1 and cancer risk is sparse." (PMID 22039442, 2011). "There is a biologic rationale for an involvement of the SLC19A1 gene in cancer risk." (PMID 22039442, 2011).